CDC25A (cell division cycle 25A)
Diseases named in the same sentence as CDC25A in open-access papers (continued):
Sharing a sentence is not in itself a finding about the gene and the disease.
tumor (continued). "CDC25A, a member of the CDC25 family of phosphatases, is highly expressed in various malignancies including HCC and proved to be associated with poor survival, which is highly consistent with our result that tumor tissues from HCC patients exhibited the upregulated CDC25A expression." (PMID 28333141, 2017). "Moreover, miR-503 has been widely described in the literature as an anti-tumor miRNA that regulates the expression of key cell cycle proteins, such as CDC25A and cyclins D1 and E1, as well as cell proliferation via E2F3 and PI3K regulation and the apoptosis status via BCL-2 inhibition." (PMID 25860935, 2015). "Key findings indicate that Episesamin targets and downregulates critical cell cycle genes CDK1, CDC25A, and PLK1, potentially inducing cell cycle arrest and inhibiting tumour growth." (PMID 40081286, 2025). "Our study highlights the importance of post-transcriptional regulation in AEG tumor progression and the clinical significance of the m6A/IGF2BP3/CDC25A axis in AEG." (PMID 39247830, 2024). "The cell cycle in tumors is modulated by c-Myc, which regulates the expression of downstream target molecules, including cyclin D1/2, cyclin E1, CDK4, cdc25A, and E2F1, and promotes tumor growth." (PMID 39085875, 2024). "In conclusion, our study highlights the role of post-transcriptional regulation in modulating AEG tumor progression and elucidates the functional importance of the m6A/IGF2BP3/CDC25A axis in AEG cells." (PMID 39247830, 2024). "Sequencing of the transformed clones revealed increased expression of several oncogenes (including CCNE2, CDC25A and CIP2A) and decreased expression of tumour suppressors providing a rationale for the observed cellular transformation." (PMID 39237765, 2024). "PART1, also known as prostate androgen-regulated transcript 1, was identified in exosomes and affected tumor progression via the miR-17-5p/SOCS6 axis and miR-302a-3p/CDC25A axis." (PMID 38279317, 2024). "Among them, we focused on CDC25A and CDK4, which were involved in tumor growth and radiosensitivity." (PMID 37173384, 2023). "In transcriptome-based public datasets generated from four different tumor types, R-PTP-κ expression was negatively correlated with the expression pattern and prognostic value of two known E2F1 target genes (CCNE1 and CDC25A)." (PMID 36551956, 2022). "The correlation between CHEK1, CDC25A, FOXK1 and tumor-infiltrating immune cells in the LIHC microenvironment was evaluated by using TIMER." (PMID 35309118, 2022). "Since phospho-Ser/Thr phosphatase cdc25A (CDC25A), cyclin E1 (CCNE1), and Myb-like protein 2 (MYBL2) have been reported as tumour promoters and are known as cell cycle regulators in NSCLC, we focused on these genes." (PMID 33883577, 2021). "In conclusion, as shown by our results and public data, CDC25A is overexpressed in STS samples and seems to be involved in tumor proliferation." (PMID 32911761, 2020). "Their common target IGF1R is a proto-oncogene, which is highly expressed in several tumor cells, CDK4 and CDC25A are proto-oncogenes." (PMID 31540229, 2019). "Eight miRNA-449-family target genes (CDC25A, SIRT1, GMNN, E2F1, E2F3, BCL2, CDK2, and CCNE2) were selected; all of them involved in tumor development, cell cycle, and apoptosis." (PMID 30926829, 2019). "In the pathway in cell cycle, we found that the expression of Ccna2, Cdc25a, Mcm3, Mcm6, Ccnb2, Mcm5, Cdk1, Gadd45a were down-regulated in the MMQ tumor stem-like cells." (PMID 28163656, 2017). "Bcl2, VEGFA, PTEN, Jun, Fos, APC2 were up-regulated and Ccna2, Cdc25a, Mcm3, Mcm6, Ccnb2, Mcm5, Cdk1, Gadd45a, Myc were down-regulated in MMQ tumor stem-like cells group." (PMID 28163656, 2017).
tumor (continued). "miR-449a has been reported to suppress tumor cell proliferation/growth and survival by targeting CDK6, CDC25A, Sirt1, HDAC1, cyclinD1, WISP2, and c-Met." (PMID 29254139, 2017). "We recently reported that a decrease in miR-184 by miR-21 promotes tumor malignancy and poor outcomes in non-small cell lung cancer (NSCLC) via targeting CDC25A and c-Myc." (PMID 27083050, 2016). "Cdc25A thereby regulates the EGFR-promoted Warburg effect, tumour cell proliferation and tumorigenesis." (PMID 27485204, 2016). "Extensive research has revealed that miR-21 is involved in proliferation, the cell cycle, metastasis and the chemosensitivity of tumor cells by targeting several tumor suppressor genes, including PTEN, MARCKS, PDCD4 and Cdc25A." (PMID 24260069, 2013). "Activated Chk1 and Chk2 increase the expression of cell cycle checkpoint proteins, including Cdc25A and Cdc25C, leading to higher levels of G2/M arrest in tumor cells treated with NPRL2 and cisplatin than in tumor cells treated with cisplatin only." (PMID 20700484, 2010). "In summary, YBX1 promotes tumor progression through its transcription factor activity, exerting its effects via various downstream targets such as MUC1, CDC25a, NANOG, Kindlin-2, G3BP1, AURKA, SPP1, the EGFR-RAS-MAPK axis, CORO1C, among others, depending on the specific tumor type." (PMID 40799245, 2025). "Further gene co-expression network analysis and prognostic analysis indicated CDK1, CCNB2, and CDC25A as the hub tumor-promoting genes in LUAD but not in LUSC, which were further validated in other datasets." (PMID 34446056, 2021). "To corroborate the USP29-mediated effect on Cdc25A-dependent oncogenic transformation in vivo, we transplanted USP29-depleted HeLa cells, USP29-depleted cells reconstituted with Cdc25A, or mock control cells into NSG mice and measured tumor volume on alternate days for four weeks." (PMID 34071237, 2021). "Moreover, both B7-H3 and CDC25A were significantly upregulated in CRC samples compared with the normal adjacent tissues and correlated with tumor stage." (PMID 32127943, 2020). "Moreover, both B7-H3 and CDC25A were significantly upregulated in CRC samples compared with normal adjacent tissues and that the levels correlated with tumor stage." (PMID 32127943, 2020). "In line with a recent study, we showed that THZ1 could suppress tumor glucose metabolism in NSCLC cells, which may depend on downregulating MYC-targeted genes including HK2, GLUT, and CDC25A." (PMID 32690037, 2020). "RNA-seq data also showed that THZ1 could diminish transcripts of MYC-targeted genes, such as HK2, CDC25A, GLUT1 (SLC2A1), PD-L1 (CD274), BRCA1, and BRCA2, which are important mediators of MYC’s function in tumor metabolism, immune evasion, and DNA repair." (PMID 32690037, 2020). "Transmission of the basal- like signature RBSP3 occurred during tumorigenesis, but the signature of LIMD1 and CDC25A was altered and hence not transmitted during development and progression of tumours." (PMID 29672635, 2018). "This study sought to determine whether CPX-induced phosphorylation and degradation of Cdc25A is through activating CK1α, GSK3β, and/or ATM/ATR-Chk1/2 in tumor cells." (PMID 29725502, 2018). "We found that CCNA2, CCNE2 and CDC25A are significantly up-regulated in PTHLH expression Ca9-22 cells and those are also up-regulated in the in Taiwanese (p < 0.01) and TCGA data (p < 0.001) HNSCC tumor." (PMID 28120940, 2017). "Taken together, our results indicate that CPX altered neither mRNA level nor protein synthesis of Cdc25A, but promoted protein degradation of Cdc25A, thereby downregulating cellular protein expression of Cdc25A in the tumor cells." (PMID 28680535, 2017). "In contrast, no tumours or much smaller tumours were detected in the mice injected with U87/EGFRvIII cells with depleted Cdc25A or reconstituted expression of rCdc25A Y59F or rPKM S37D mutant." (PMID 27485204, 2016).
tumor (continued). "Moreover, target genes frequently upregulated in HCC in a tumor-specific manner, such as CDK6, CCNE1, CDC25A and CDK4, showed an inverse correlation in the expression of miR-195 and miR-497, and their targets." (PMID 23544130, 2013). "Meanwhile, among the target genes for miR-195 and miR-497 identified in the present study, top four target genes, CCNE1, CDC25A, CDK4 and CDK6, frequently upregulated in a tumor-specific manner only showed slight inverse correlation with these miRNAs in HCC tumors." (PMID 23544130, 2013). "In a re-analysis of those data, one prominentgene-expression feature included genes regulating the cell-cycle (e.g. CCNE1,CDK1, CDC25A), and involved in DNA replication(e.g. POLE2, MCM4, TK1) andchromosome dynamics (e.g. SMC4, CENPE), ostensiblyreflecting tumor cell proliferation levels." (PMID 21629784, 2011). "Although we did not study directly expression of cdc25A in these tumours, we found that overexpression of cyclin A is significantly associated with worse outcome in tamoxifen treated patients (P=0.0462)." (PMID 11875707, 2002). "The tumor tissues were then analyzed by Western blotting to detect the different expression levels of proliferation (Ki67 and PCNA), apoptosis (c-Casp3, c-PARP), metastasis (vimentin), related substrate (p-PDH, HDAC1), and cell cycle-related proteins (CDC25A, CDK4, CDK6, and Rb) in each group." (PMID 38948069, 2024). "Taken together, this study reports that replication stress induced by overexpression of Cyclin E1 and Cdc25A results in the formation of lagging chromosomes and chromatin bridges, which is further exacerbated by inhibition of ATR or WEE1 kinases, and results in exacerbated tumor cell killing." (PMID 33028815, 2020). "However, the basal- like signature of LIMD1 and CDC25A was not transmitted during tumour development." (PMID 29672635, 2018). "Therefore data from clinical HNSCC patients also demonstrate that PTHLH might regulate tumor growth through cell cycle regulators, namely, CCNA2, CCNE2, and CDC25A." (PMID 28120940, 2017). "CDC25A, a cell cycle-related gene, was not part of any network, but was highly DE and likely influences cell cycle and differentiation in bronchial epithelium during inflammation, as it does in other contexts such as neoplasia." (PMID 28886691, 2017). "Taken other line of evidence together, a possible role of miR-21 as an oncogene has been hypothesized, including proliferation, cell cycle, metastasis, and chemosensitivity of tumor cells by targeting several tumor suppressor genes such as PTEN, MARCKS, PDCD4, and Cdc25A." (PMID 22792096, 2012). "In this study, pBD2 showed anti-tumor potential by upregulating the expression of PTEN and downregulating the expression of SPRY2 and PLAU, and pBD2 was also shown to promote cell proliferation by upregulating the expression of CDC25A, E2F2, and PTGS2, which perhaps might lead to tumorigenesis." (PMID 36077151, 2022). "Finally, analysis of polysomal RNAs from livers of CTL and TIA1 knockdown LPTENKO mice indicated that consistent with a lack of effect of TIA1 downregulation on tumor growth and progression, markers for proliferation (Mki67, Pcna, Cdkn1a, Cdkn1b, Cdc25a) and inflammation (Il1b, Tgfb) were unchanged." (PMID 35406476, 2022). "After excluding non-informative tumor samples (21 of 178 at SH3GL2 and 60 of 178 at CDC25A locus), high frequency of deletion was observed in SH3GL2 (34%, 54/157) and CDC25A (52%, 56/108) loci." (PMID 23675485, 2013).
infection (8 papers, 2011 to 2018). The state of being infected such as from the introduction of a foreign agent such as serum, vaccine, antigenic substance or organism. "MVM infection induced Chk2 activation early in infection which led to a transient S-phase block associated with proteasome-mediated CDC25A degradation." (PMID 24415942, 2014). "It is notable that in Tab182- and CNOT1-depleted cells, there is only a very limited induction of CDC25A after infection, whereas this is appreciable in control infected cells." (PMID 29593045, 2018). "Of interest, infection with Ad-Cdc25A-wt, Ad-Cdc25A-S76A or Ad-Cdc25A-S82A upregulated the Cdc25A protein levels by 1.5∼1.8 fold, compared to infection with Ad-GFP." (PMID 28680535, 2017). "To confirm these data, we performed lentiviral infection of MOLM-14 cells with an shRNA targeting CDC25A." (PMID 26515730, 2015). "This was further confirmed by assaying Cdc25A and showing that the levels of this protein also dropped 1 day after infection." (PMID 21853057, 2011). "This early S-phase arrest was important for viral replication; however, Chk2 activation and CDC25A loss were not sufficient to sustain the marked G2 arrest seen following MVM infection." (PMID 24415942, 2014). "Chk2 activation and CDC25A loss were alone not sufficient to sustain the G2 arrest seen following MVM infection." (PMID 24415942, 2014). "This step was necessary for efficient viral replication; however, Chk2 activation and CDC25A loss were not sufficient to keep infected cells in the sustained G2-arrested state which characterizes this infection." (PMID 24415942, 2014). "The pAd-DsRed-IRES-EGFP-Cdc25A reporter was generated using this adenovirus vector cloned with the Cdc25A ORF, and it easily reached >95% infection efficiency in HeLa cells." (PMID 27462461, 2016). "QRT-PCR analysis revealed that at early stage of infection (day 1 p.i.), mRNA levels of cell cycle genes such as CDC2, CDC25A, Cyclin E, CDK5, CDK8 and Cyclin G1 were significantly (P<0.05) upregulated in A. phagocytophilum-infected cells in comparison to uninfected controls." (PMID 28797056, 2017). "Chk2 activation and CDC25A loss, however, were not sufficient to induce the dramatic G2 arrest seen following MVM infection." (PMID 24415942, 2014). "Down-regulation of CDC25A induced CD11b and CD14 expression 3 and 6 days after infection respectively, while CD15 expression was decreased, confirming the data obtained by pharmacological inhibition and further arguing for the implication of CDC25A in the differentiation process." (PMID 26515730, 2015).
adenocarcinoma (4 papers, 2016 to 2024). A common cancer characterized by the presence of malignant glandular cells. "Notably, 4 of the glucose metabolism-related genes, GPI, G6PD, PKM2, and GAPDH and 5 of the cell cycle-related genes, ANLN, PTTG1, CIT, KPNA2, and CDC25A, were significantly down-regulated in EGFR m+ adenocarcinomas, and showed a substantial correlation with SUVmax." (PMID 28422979, 2017). "More interestingly, the patients with MIA, a less aggressive subtype of adenocarcinoma, had neither YBX1 nor CDC25a high expression in accordance with IASLC/ATS/ERS international multidisciplinary classification." (PMID 27384875, 2016).
CDC25A also shares sentences with these, for which no sentence is quoted: rhabdomyosarcoma (3 papers); liposarcoma (2); lung squamous cell carcinoma (2); lymph node metastasis (2); lymphoma (2); thyroid carcinoma (2); allergic rhinitis (1); asthma (1); Azoospermia (1); brain cancer (1); brain tumour (1); cervical tumours (1); cholangiocarcinoma (1); chondrosarcoma (1); cocaine addiction (1); cyst (1); cystic liver disease (1); diffuse astrocytoma (1); esophagogastric junction adenocarcinoma (1); Fanconi anemia (1); follicular adenoma (1); follicular carcinoma (1); head and neck squamous cell carcinoma (1); hearing loss (1); kidney chromophobe (1); kidney tumors (1); liver (1); liver fibrosis (1); metastatic diseases (1); multiple myeloma (1).
A further 14 diseases each share a sentence with CDC25A in 1 paper.